NPY4R (neuropeptide Y receptor Y4)
Description:
G protein-coupled receptor for PPY/pancreatic polypeptide/PP, NPY/neuropeptide Y and PYY/peptide YY that is negatively coupled to cAMP. The rank order of affinity for these polypeptides and their derivatives is PP, PP (2-36) and [Ile-31, Gln-34] PP > [Pro-34] PYY > PYY and [Leu-31, Pro-34] NPY > NPY > PYY (3-36) and NPY (2-36) > PP (13-36) > PP (31-36) > NPY free acid.
Synonyms: NPY4-R; PP1; PPYR1; Y4
Tractability: Small molecule: a high-quality ligand is known; it belongs to a druggable protein family. Antibody: UniProt places it where antibodies can reach, with high confidence; its Gene Ontology location is reachable by antibodies, with high confidence; UniProt predicts a signal peptide or a membrane-spanning region. PROTAC: ubiquitination databases record sites on it; a small molecule that binds it is known.
Target class: Neuropeptide Y receptor; Peptide receptor (family A GPCR); Membrane receptor; Family A G protein-coupled receptor; Short peptide receptor (family A GPCR)
Chemical probes: CHEMBL2440193, CHEMBL408891
Gene: Protein-coding gene on chromosome 10 (46,457,895 to 46,465,958, reverse strand). Ensembl gene ENSG00000204174.
Subcellular location: Cell membrane
Pathways (Reactome):
Signal Transduction: G alpha (i) signalling events; Peptide ligand-binding receptors
Gene Ontology:
Molecular function: pancreatic polypeptide receptor activity; peptide hormone binding; protein binding; G protein-coupled receptor activity; peptide YY receptor activity; neuropeptide Y receptor activity
Biological process: G protein-coupled receptor signaling pathway; neuropeptide signaling pathway
Cellular component: membrane; plasma membrane; neuron projection
Genetic constraint (gnomAD): Loss-of-function variants: 1 observed, 2.47 expected, observed/expected ratio (o/e) 0.4, 90% interval 0.14 to 1.62. That is too few expected variants to judge how well the gene tolerates losing a copy. Missense variants: 11 observed, 65.51 expected, observed/expected ratio (o/e) 0.17, 90% interval 0.1 to 0.28. Synonymous variants: 4 observed, 25.95 expected, observed/expected ratio (o/e) 0.15, 90% interval 0.075 to 0.35.
Homologues: Orthologues: chimpanzee NPY4R (99% identical), macaque NPY4R (95% identical), dog NPY4R (86% identical), guinea pig Npy4r2 (83% identical), rabbit NPY4R (82% identical), mouse Npy4r (75% identical), tropical clawed frog XB996286 (48% identical). Paralogues in human: NPY4R2 (99% identical), NPY1R (44% identical), PRLHR (30% identical), NPY2R (27% identical), GPR83 (26% identical), NPY5R (26% identical), TACR1 (24% identical), TACR3 (24% identical), TACR2 (23% identical), PROKR1 (22% identical), PROKR2 (22% identical), MTNR1B (20% identical), and 21 more.
Diseases named in the same sentence as NPY4R in open-access papers:
NPY4R is named in the same sentence as 14 diseases in open-access papers, as found by Europe PMC text mining. Sharing a sentence is not in itself a finding about the gene and the disease. The quoted sentences say what the papers report.
Obesity (8 papers, 2017 to 2025). Accumulation of substantial excess body fat. "There are presently no data on the role of NPY4R in cancer, despite the fact that genetic and structural variation within the NPY4R gene has been linked to obesity onset." (PMID 35831825, 2022). "Among the genes located in the region, NPY4R was the strongest candidate for association with obesity and was found to have nonsynonymous single nucleotide polymorphisms (SNPs) that segregated with childhood obesity." (PMID 29621259, 2018). "The specific NPY4R agonist, BA-129 inhibits the proliferation of pancreatic cancer cells in vitro, and genetic and structural variations in NPY4R have been implicated in the pathogenesis of obesity." (PMID 29100314, 2017). "The regions showing association with obesity‐related phenotypes are located at 11q11 (OR4P4, OR4S2, OR4C6), 1p21.1 (AMΥ1), 10q11.22 (NPY4R), 10q26.3 (CYP2E1), 16q12.2 (FTO), 16p12.3 (GPRC5b), and 4q25 and have been associated with adult obesity as well." (PMID 41082226, 2025). "(Proline3)PP, or (P3)PP, is an enzymatically stable, neuropeptide Y4 receptor (NPY4R)-selective, pancreatic polypeptide (PP) analogue with established weight-lowering and pancreatic islet morphology benefits in obesity-diabetes." (PMID 40362452, 2025). "Firstly, the sample size was insufficient to detect associations of obesity with low frequency alleles (1p31.1/NEGR1, 10q11.22/GPRC5B, and 16p12.3/NPY4R), although it was sufficient to find associations with 11q11/OR4P4/OR4S2/OR4C6, and 1p21.1/AMY1 CNs." (PMID 30388780, 2018). "To address the relationship between NPY4R copy number and obesity, we present here a study of 558 individuals with a wide range of BMIs." (PMID 29621259, 2018). "npy4r knockout mice showed that npy4r promotes obesity induced by high fat diet." (PMID 38020893, 2023). "Due to the CNV and the role of NPY4R and its ligand pancreatic polypeptide in the regulation of food intake, this gene is a strong candidate for contribution to body weight variation and obesity." (PMID 31164119, 2019). "Finally, previous studies associating the NPY4R CNV with obesity risk have reported contradictory findings, as the CNV deletion allele has been associated both with higher and lower obesity risk." (PMID 30388780, 2018). "A study of 799 young Chinese individuals could not detect CNV of NPY4R, neither in subjects with obesity nor in subjects with normal weight." (PMID 29621259, 2018).
Anxiety (3 papers, 2020 to 2025). Intense feelings of nervousness, tension, or panic often arise in response to interpersonal stresses. "NPY4R and NPY4R2 encode neuropeptide Y receptors; neuropeptide Y is a gut-brain peptide which modulates multiple physiologic processes, including feeding behavior and anxiety." (PMID 32780866, 2020). "hsa-miR-16a-5p targets BDNF, NPY4R, and GLUD1, which have been reported to be involved in the pathophysiology of anxiety and depression." (PMID 39821903, 2025). "Furthermore, miR-16-5p was predicted to target to BDNF, NPY4R, GLUD1, and FKBP5, which are reported to be involved in the pathophysiology of anxiety and depression." (PMID 33737514, 2021).
diabetes (1 paper, 2025). "We have confirmed that NPY4R agonists impart disease-modifying advantages on pancreatic islets in diabetes, associated with positive actions on the plasticity of both alpha- and beta-cells." (PMID 40362452, 2025). "This likely reflects the severity of the multiple-low-dose STZ model of diabetes, and the propensity for NPY4R to restore normal metabolism." (PMID 40362452, 2025).
glioblastoma (1 paper, 2025). The most malignant astrocytic tumor (WHO grade IV). "The neuropeptide-related genes, including PPY and members of the NPY family (e.g., NPY, NPY1R, NPY2R, NPY4R, NPY5R, PYY), form a distinct cluster characterized by strong co-expression and shared pathway interactions, indicating a potential role in neuroendocrine signaling relevant to glioblastoma." (PMID 40725410, 2025).
Hyperinsulinemia (1 paper, 2015). An increased concentration of insulin in the blood. "In mice, a triple knockout of NPY1R, NPY2R and NPY4R prevents the hyperinsulinemia associated with NPY overexpression, indicating that NPY signalling through the NPY receptors modulates insulin secretion." (PMID 26138755, 2015).
hypothyroidism (1 paper, 2021). Abnormally low levels of thyroid hormone. "In our study, the expression of the NPY4R gene that encodes the Y4 receptor is increased in patients with postoperative hypothyroidism." (PMID 34104248, 2021). "Our research found that patients with postoperative hypothyroidism had a considerably increased expression of NPY1R, NTSR1, and NPY4R." (PMID 34104248, 2021). "Our research identified that patients with postoperative hypothyroidism had a considerably increased expression of NPY1R, NTSR1, and NPY4R." (PMID 34104248, 2021). "The absence of changes in the expression of NPY4R in patients with AIT-related hypothyroidism and a group of patients with rising serum autoantibodies suggests that the high level of serum autoantibodies, such as anti-Tg and anti-TPO, do not affect the expression of NPY4R." (PMID 34104248, 2021).
oropharyngeal cancer (1 paper, 2017). Carcinoma, predominantly squamous cell, arising from the epithelial cells of the oropharynx. "Our study associates NPY1R, NPY2R, and NPY4R methylation with tumor recurrence in oral and oropharyngeal cancers." (PMID 29100314, 2017). "Similar findings were observed for NPY2R and NPY4R in patients with oropharyngeal cancer (n = 162) (odds ratio, 5.663; 95% CI, 1.507–21.28; P = 0.010)." (PMID 29100314, 2017). "The present study suggests that the methylation status of the NPY1R, NPY2R, and NPY4R genes is an independent indicator of DFS in patients with oral and/or oropharyngeal cancers." (PMID 29100314, 2017).
Rett syndrome (1 paper, 2018). A severe neurodevelopmental disorder affecting the central nervous system. "In contrast, a study of 12 females with Rett syndrome found a positive correlation of NPY4R copy number with weight gain." (PMID 29621259, 2018).
NPY4R also shares sentences with these, for which no sentence is quoted: cancer (1 paper); depression (1); Esotropia (1); Hypertension (1); pancreatic cancer (1); tumor (1).